BRAF (B-Raf proto-oncogene, serine/threonine kinase)
Diseases named in the same sentence as BRAF in open-access papers (continued):
Sharing a sentence is not in itself a finding about the gene and the disease.
sarcoma (51 papers, 2011 to 2026). A usually aggressive malignant neoplasm of the soft tissue or bone. "Few cases have reported BRAF mutations and outcomes of BRAF-targeted therapy in various sarcoma types." (PMID 40909947, 2025). "Since BRAF is activated by point mutations (most frequently BRAF V600E) and translocations in a large number of tumors also outside the sarcoma field, it has been in focus as a target for therapy for quite a while." (PMID 38611033, 2024). "Another study screened for the presence of the BRAF mutation in 667 canine tumours, including a series of haematopoietic tumours (n = 245), sarcomas (n = 160), carcinomas (n = 115), melanocytic tumours (n = 72), as well as other, less common cancers (n = 75)." (PMID 35324835, 2022). "Similar to other malignant tumors, BRAF mutations are also present in sarcomas but with a very low frequency." (PMID 34356494, 2021). "CDK4 amplification was present in all but one dedifferentiated liposarcoma, and two potentially targetable mutations of the BRAF/MAPK pathway were detectable in undifferentiated (pleomorphic) sarcomas." (PMID 34356494, 2021). "Responder patients had mutations around the rapidly accelerated fibrosarcoma (RAF)-rat sarcoma (RAS)-ERK pathway including KRAS/BRAF and MEK-related mutations that predicted the profiles to have stronger expression of PD-L1." (PMID 29486723, 2018). "In the STS cohort, BRAF V600E mutations were identified in patients diagnosed with sarcoma NOS (n=4), angiosarcoma (n=2), solitary fibrous tumor (n=1), desmoid fibromatosis (n=1), round cell sarcoma NOS (n=1), embryonal rhabdomyosarcoma (n=1), and undifferentiated pleomorphic sarcoma (n=1)." (PMID 36741731, 2022). "The other potentially druggable mutation we could identify here was a BRAF V600E mutation in another undifferentiated (pleomorphic) sarcoma." (PMID 34356494, 2021). "In addition, two potentially druggable mutations, a MAP2K1 missense mutation (E203K) and a BRAF missense mutation (V600E), were traceable in two undifferentiated (pleomorphic) sarcoma patients (11%; 2/18)." (PMID 34356494, 2021). "However, to our knowledge, there are few clinical trials about the treatment of sarcoma patients with the BRAF V600E mutation treated with BRAF inhibitors, and most reports of sarcoma patients treated with BRAF inhibitors are case reports." (PMID 32476297, 2020). "In addition to shared clonal abnormalities, additional aberrancies were detected in the sarcoma tumor cells, including deletion of a subclone of BRAF (G466A), loss of TRAF3 R505 and new clonal mutations in NF1 and TNFAIP3." (PMID 29463311, 2018). "Thus far, only singular case reports have suggested that BRAF inhibitors in combination with MEK inhibitors (dabrafenib/trametinib) could result in a good response in BRAF V600E-mutated sarcoma." (PMID 34356494, 2021). "Similarly, the classification of BRAF mutations, the knowledge about dysregulated signaling pathways and dysregulated circuitries related to these mutations, and the function of BRAF in sarcoma led to the development of new therapeutic options to overcome resistance to conventional chemotherapy." (PMID 33047515, 2020). "Nevertheless, further studies are needed to define the prognostic features of these emerging BRAF sarcomas, along with new anti-BRAF therapeutic approaches." (PMID 39940949, 2025). "Nevertheless, further studies are needed to define the prognostic features of these emergent BRAF sarcomas." (PMID 39940949, 2025). "BRAF fusions have been detected in different sarcomas of the fibroblastic/myofibroblastic arm of sarcoma." (PMID 38611033, 2024). "Several clinical cases of successful targeted therapy (TT) in patients with BRAF V600E-positive sarcomas have been published." (PMID 39018206, 2024). "BRAF and ERBB2 mutations, however, specifically BRAF V558E and ERRB2 V659E, are depleted in sarcoma." (PMID 37414794, 2023).
sarcoma (continued). "In this article, we review the therapeutic efficacy of BRAF inhibitors in sarcomas, and summarize the mechanism of resistance to BRAF inhibitors and the combination with other targeted drugs." (PMID 32476297, 2020). "The levels of mRNA and protein for both wild-type and mutated BRAF were similar in both SA-4 and SW872 sarcoma cell lines." (PMID 29570692, 2018). "Most importantly, we summarize the results of BRAF inhibitor treatment in different sarcomas." (PMID 32476297, 2020). "To assess whether the sarcoma cell lines with a poor or short-term effect on cell growth circumvent the need for BRAF to be able to phosphorylate ERK, we evaluated the levels of p-ERK protein following treatment with vemurafenib for 3 or 72 h." (PMID 29570692, 2018). "Additionally, PDE10A::BRAF fusions have been reported in rare pediatric sarcomas." (PMID 41179677, 2025). "A study analyzed 108 sarcoma samples by gene sequencing, and the data showed that the BRAF mutation was not common, suggesting that the BRAF mutation might not cause malignancy." (PMID 32476297, 2020). "In addition, other case reports have also reported that BRAF inhibitors are effective for sarcoma." (PMID 32476297, 2020). "Similarly, although unexpectedly, we discovered that 3 STS cell lines SW872, SW982 and GCT contained a BRAF V600E mutation, a recent study found that none of the samples from 108 sarcoma patients were BRAF mutation positive." (PMID 28556791, 2017). "Similarly, a recent study found that none of the samples from 108 sarcoma patients were BRAF mutation positive." (PMID 26909593, 2016). "In a recent large study of sarcoma, CGP identified potentially actionable kinase fusions (including NTRK1‐3, ALK, BRAF, FGFR1‐4, RET, and ROS1) in 2.6% of patients." (PMID 38925616, 2024). "Besides two non-synonymous mutations in MAP2K1 (p.Q203K) and BRAF (p.V600E), which both occurred in pleomorphic (undifferentiated) sarcomas (P06, P11), no further mutations could be detected with the OFA." (PMID 34356494, 2021). "Then a descriptive diagnosis of BRAF rearrangement sarcoma with moderate-grade malignancy (non-specific type) was given according to the biological behavior, morphological features and gene alteration." (PMID 38606111, 2024). "These included ALK, BRAF, FGFR1–4, NTRK1–3, RET, and ROS1 kinase fusions in a wide range of sarcoma histologies, including IMT (62.1%), MPNST (4.9%), UPS of bone (4.3%), extraskeletal osteosarcomas (4%), UPS (3.6%), sarcoma NOS (3.8%), and LMS (1.9%)." (PMID 35705558, 2022). "No specific sarcoma differentiation was apparent in the stroma by immunohistochemistry, and no SYT-SS18 rearrangement or BRAF mutation was detected by molecular analysis." (PMID 25267074, 2014). "Interestingly, BRAF fusions have recently been reported in a subset of NTRK fusion negative pediatric sarcomas showing morphologic overlap with IFS." (PMID 32490123, 2020). "Therefore, it is worth determining whether the combination of BRAF inhibitors and MEK inhibitors can have the same effect in sarcomas." (PMID 32476297, 2020). "STARD3NL::BRAF fusion has earlier been described at least in one paediatric sarcoma, whereas to our best knowledge, LMTK2::BRAF has not been reported before in any tumour type." (PMID 35237889, 2022).
RASopathy (49 papers, 2014 to 2025). Developmental syndromes caused by germline mutations (or in rare cases by somatic mosaicism) in genes that alter the Ras subfamily and mitogen-activated protein kinases that control signal transduction. "Our results demonstrate that ERK hyperactivity contributes to astrocyte dysfunction associated with Ca2+ dysregulation, leading to the memory deficits of BRAF-associated RASopathies." (PMID 39964758, 2025). "In this study, we demonstrate that the BRAF KE mutation associated with several RASopathies induces hyperactive RAS/ERK signaling that disrupts normal astrocytic cell function, impairing hippocampal learning and memory." (PMID 39964758, 2025). "Consistent with our findings in Nestin;BRAFKE/+ mice, mouse models carrying the BRAF V600E mutation showed multiple RASopathy-like phenotypes and also exhibited increased GFAP+ cells in the hippocampus and cortex, regardless of their genetic background." (PMID 39964758, 2025). "Many of the RASopathy-associated genes are in gene families: RAF (BRAF and RAF1), RAS (HRAS, KRAS, MRAS, NRAS, RIT1, and RRAS2), MAP2K (MAP2K1 and MAP2K2), and SOS (SOS1 and SOS2)." (PMID 40496714, 2025). "Here, we investigated the underlying neural mechanisms using several mouse models harboring a gain-of-function BRAF mutation (K499E) discovered in RASopathy patients." (PMID 39964758, 2025). "Mutations in the BRAF gene are frequently associated with RASopathies including CFC syndrome and Noonan syndrome." (PMID 39964758, 2025). "A RASopathy-associated gain-of-function BRAF mutation induces hippocampal memory deficits through elevated ERK activity and aberrant calcium signals in reactive astrocytes." (PMID 39964758, 2025). "Germline activating variants affecting either BRAF or other members of the RAS-RAF-MEK-ERK pathway are associated with a group of developmental syndromes collectively known as RASopathies." (PMID 38067388, 2023). "The multigene RASopathy panel identified the maternally inherited heterozygous variant c.26G>C, p.(Gly9Ala) in BRAF (NM_004333.6, MIM*164757), classified as VUS." (PMID 36611340, 2022). "Our findings show a critical role of BRAF in hypothalamo-pituitary-axis development both in mouse and human and implicate mutations found in RASopathies as a cause of endocrine deficiencies in humans." (PMID 33795686, 2021). "Here we highlight a case of a family who received a report of a variant (c.622A>G, p.Ile208Val) in BRAF following prenatal RASopathy testing." (PMID 29945942, 2018). "Cardio-facio-cutaneous syndrome (CFC) is a rare RASopathy associated with mutations in BRAF, KRAS, MEK1 (MAP2K1) and MEK2 (MAP2K2)." (PMID 29590634, 2018). "Some of these genes increase predisposition to cancer, for example, in rasopathies, and BRAF, KRAS, HRAS, NF1, NRAS PTPN11, RAF129." (PMID 27080396, 2016). "This is reflected by the various germ-line BRAF mutations found in the neuro-cardio-facio-cutaneous syndromes or RASopathies." (PMID 27034005, 2016). "Mutations in BRAF have been associated with RASopathies, most commonly cardiofaciocutaneous syndrome (CFC) but also Noonan and LEOPARD syndrome." (PMID 26064708, 2015). "In addition to intellectual disability, individuals with RASopathy that express BRAF mutations often display a broad range of behavioral disabilities such as locomotor impairments, increased anxiety, and decreased sociability." (PMID 39964758, 2025). "Several mouse models carrying RASopathy-associated BRAF mutations have been characterized." (PMID 39964758, 2025). "The mechanisms underlying these cognitive deficits observed in BRAF-associated RASopathies, however, remain largely unknown." (PMID 39964758, 2025).
RASopathy (continued). "To address this knowledge gap, we asked whether BRAF K499E (KE), a constitutively active mutation associated with multiple RASopathies, affects astrocytes and contributes to learning and memory deficits in mice." (PMID 39964758, 2025). "This, along with the phenotypic differences of mouse models with different genetic backgrounds, suggests RASopathy-associated BRAF mutations exert heterogenous effects on downstream signaling pathways depending on the way each mutation interacts with each genetic background throughout development." (PMID 39964758, 2025). "Notably, mutations that alter BRAF function are prominent drivers of human cancer and certain RASopathy disorders, making BRAF an important target for therapeutic intervention." (PMID 40894786, 2025). "Recently, the role of the BRAF gene in BRAF-associated RASopathies has been extensively described." (PMID 40563584, 2025). "In this study, we used conditional knockin mice, adeno-associated virus (AAV) vectors, and human cortical spheroids expressing BRAF KE to implicate astrocyte dysfunction due to ERK hyperactivity in the learning and memory deficits of BRAF mutation-associated RASopathies." (PMID 39964758, 2025). "Estimations of Sanger sequencing prices were performed for five genes most commonly associated with RASopathies (BRAF, NF1, PTPN11, RAF1, and SOS1), and three genes, TCOF1, CHD7, and NIBPL most commonly associated with Treacher Collins, CHARGE, and Cornelia de Lange syndromes, respectively." (PMID 37815686, 2024). "Interestingly, approximately 40% of Rasopathy BRAF mutations alter amino acids predicted to mediate interactions between Ras and the cysteine-rich domain (CRD) of B-Raf." (PMID 37681415, 2023). "While RASopathy mutations in BRAF are centered within the CRD, our results imply that the mutations may also affect the ability of the BSR to regulate BRAF autoinhibition." (PMID 38150000, 2023). "She received a report of a variant in BRAF following prenatal RASopathy testing." (PMID 34702330, 2021). "Indeed, patients with cardiofaciocutaneous syndrome (an infrequent RASopathy) caused by activating germline BRAF variants may also develop pituitary hormone deficiencies." (PMID 38067388, 2023). "Genes involved in the sutures of the cranial bones, microcephaly, closure of the neural tube (e.g., VANGLI1), and in RASopathy (e.g., BRAF and CBL) were also identified." (PMID 39458107, 2024). "The RAS-regulated ERK1/2 signalling pathway is frequently activated in cancer and developmental syndromes (RASopathies) due to activating mutations in a variety of pathway components including the RAS proteins (especially KRAS), BRAF, CRAF, MEK1 and MEK2." (PMID 38381045, 2024). "Multigene panel for common RASopathy genes that includes BRAF, MAP2K1, MAP2K2, KRAS and YWHAZ usually detects up to 90% of individuals with CFC and it is the preferred initial test." (PMID 38136934, 2023). "NS is the most common type of RASopathy, and is a rare genetically heterogeneous autosomal dominant disorder caused by mutations in either the PTPN11, SOS 1, KRAS, BRAF or RAF1 genes." (PMID 37106005, 2023). "Expression of this variant in Xenopus tropicalis increased BRAF and RAF1 binding, ERK phosphorylation and decreased body length, consistent with YWHAZ functioning as a RASopathy gene." (PMID 35178568, 2022). "RAS then signals to numerous downstream effector pathways via serine/threonine kinase RAF (ARAF, BRAF and CRAF/RAF1), which, when dysregulated in the germline, causes RASopathies." (PMID 35103797, 2022). "MEK inhibition also reversed RASopathy phenotypes in PTPN11- and NRAS-associated zebrafish models of NS, BRAF- and MAP2K1-associated zebrafish models of CFC, and ARAF-associated zebrafish models of CCLA." (PMID 35178568, 2022).
RASopathy (continued). "Phosphorylation of the RASopathy proteins RAF1, PTPN11, and BRAF is altered in NS and NSML due to mutations in their corresponding genes, whereas RASA1 altered phosphorylation is associated to mutant SHP2 models and not to its own mutation." (PMID 34229750, 2021). "Germline mutations in BRAF and other components of the MAPK pathway are associated with the congenital syndromes collectively known as RASopathies." (PMID 33795686, 2021). "Found in perhaps 1:1000 new births, RASopathies are associated with variants in genes encoding multiple RAS pathway components including KRAS, NRAS, BRAF, RAF1, and SHP2." (PMID 33855281, 2021). "We generated a RASopathy disease model using IQ-Switch and demonstrated that the RASopathy symptoms were ameliorated by the specific BRAF(V600E) inhibitor vemurafenib, validating the therapeutic use of the gene switch." (PMID 34916605, 2021). "In addition, variants were identified in a wide range of other RASopathy-associated genes, including LZTR1, BRAF, SOS1, and RAF1, underscoring the necessity of broad genetic testing approaches such as WES in cases with overlapping phenotypes." (PMID 41292581, 2025). "Given the relation to mosaic RASopathies involving hyperactivation of the RAS-MAPK-MEK pathway, MEK inhibitors have shown some initial promise in case reports of congenital melanocytic lesions with activating genetic variants in NRAS and mosaic BRAF fusions." (PMID 41523454, 2025). "The RASopathies, collectively, are a spectrum of genetic syndromes caused by mutations in genes involved in the RAS/ mitogen-activated protein kinase (MAPK) pathway, including but not limited to PTPN11, NRAS, KRAS, HRAS, BRAF, and MAP2K1." (PMID 39385823, 2024). "In addition to the well-characterized NRAS, KRAS, and BRAF genes, our study revealed that the germline Rasopathy genes represent a long tail of somatic alterations linking MM to these rare, congenital RAS-pathway-related diseases." (PMID 35768438, 2022). "Indeed, the tool compound U0126, which inhibits MEK in part due to its ability to chelate copper, is effective in reversing RASopathy phenotypes in iPSCs derived from patients with RAF1-associated NS and in BRAF- and MEK-associated CFC." (PMID 35178568, 2022). "Interestingly, in addition to patients with KRAS, NRAS, and BRAF mutations, we found that MM exhibited a long tail of alterations in rare, congenital RAS-pathway-related diseases, known as the “Rasopathies”." (PMID 35768438, 2022). "RASopathies represent a family of mostly autosomal dominant diseases that are caused by missense variants in the rat sarcoma viral oncogene/mitogen activated protein kinase (RAS/MAPK) pathway including KRAS, NRAS, BRAF, RAF1, and SHP2." (PMID 33855281, 2021). "In addition, we verified by exomeanalysis that the patient did not have any pathogenic variants in the genes associatedwith Noonan Syndrome and other rasopathies (PTPN11,SHOC2, KRAS, CBL,SOS1, RAF1, HRAS,NRAS, RASA1, SPRED1,BRAF, MAP2K1, MAP2K2, RIT1 andRRAS)." (PMID 27561113, 2016). "At the present time, RASopathies are categorized as separate syndromes, but, as we learn more about each syndrome, clinically defining a RASopathy may be more accurately approached based on the molecular diagnosis, or gene name, such as a BRAF-based RASopathy or an HRAS-based RASopathy." (PMID 35103797, 2022). "BRAF, CBL, NF1, PTPN11, RAF1, SOS1 and SOS2 contain at least 20 phosphosites each, and they account for 326 of the phosphosites identified in RASopathy proteins (61% of the total)." (PMID 34229750, 2021). "Expressing human RASopathy isoforms of KRAS, HRAS, RAF1, BRAF, and PTPN11 in Drosophila, we report important differences between disease isoforms including distinct signaling pathways and drug responses." (PMID 33855281, 2021).